AKR1C1 (aldo-keto reductase family 1 member C1)
Diseases named in the same sentence as AKR1C1 in open-access papers (continued):
Sharing a sentence is not in itself a finding about the gene and the disease.
cancer (continued). "Thus, to reveal the potential mechanism of upregulation of AKR1C1, we focused on the miRNAs, one of the most common and well-studied epigenetic mechanisms in cancers." (PMID 38472205, 2024). "Overexpression of Nrf2 and AKR1C1 may be one of the main molecular mediators of progesterone resistance in patients with endometrial precancerous lesions and well-differentiated cancers." (PMID 37810967, 2023). "Overexpression of AKR1C1 has been found to be involved in cancer initiation and progression, and it could contribute to proliferation and cell-death evasion in cancer cells." (PMID 35370661, 2022). "In particular, AKR1C1/2 detoxify ROS which leads to cancer progression." (PMID 35115586, 2022). "Given our previous data, we hypothesized that the downstream gene of NRF2 pathway, AKR1C1, might protect cancer cells from cytotoxic effects of chemotherapy through its inhibitory effect on progesterone metabolism." (PMID 35115586, 2022). "Moreover, AKR1C1 overexpression correlates with drug resistance in some cancer cell lines to chemotherapy in vitro." (PMID 35370661, 2022). "Therefore, it is of substantial interest to explore more compounds that directly bind to AKR1C1 to suppress cell proliferation and metastasis for effective cancer therapy." (PMID 35370661, 2022). "AKR1C1 protects cancer cells from ferroptosis and is considered as the ferroptosis-protective gene." (PMID 34249766, 2021). "AKR1C1 is reportedly involved in the initiation and progression of cancer." (PMID 34012402, 2021). "AKR1C1 expression is related to development and metastasis of many types of cancer." (PMID 34127944, 2021). "Moreover, in consistent with previous studies, AKR1C1 expression in carcinoma cells correlated positively with DFS and OS of CCA." (PMID 34127944, 2021). "AKR1C1 has been therefore proposed as a potential target for cancer therapy." (PMID 32104503, 2020). "The seemingly contradicting conclusions of these two independent studies may arise from the different cellular context of the two types of cancer models, as well as the varied choices of AKR1C1 inhibitors." (PMID 32104503, 2020). "The NRF2/AKR1C1 pathway may represent a new therapeutic strategy for treatment of endometrial hyperplasia/cancer." (PMID 32370225, 2020). "Because AKR1C1 works as cellular ROS scavenger and up-regulation in cancer-stem cells which hint that AKR1C1 might be a broad-range chemoresistance gene in cancer." (PMID 31182137, 2019). "We further examined the cancer sphere formation ability of AKR1C1, which could increase the cancer spheroids in Cal-27 cells." (PMID 31182137, 2019). "Targeting the Nrf2/AKR1C1 pathway may represent a new therapeutic strategy for treatment of endometrial hyperplasia/cancer." (PMID 26824415, 2016). "Previous studies have observed altered expression of AKR1C1 in a variety of human cancers." (PMID 24003325, 2013). "Overall, these results recapitulate the in vitro observations and suggest that AKR1C1 depletion could render cancer cells more sensitive to ferroptosis and the combination of targeting AKR1C1 with ferroptosis inducers might represent a promising strategy for ECC treatment." (PMID 39478199, 2025). "Thus, we were encouraged to speculate that AKR1C1 might play a critical role in the cancer initiation and progression of NSCLC." (PMID 35370661, 2022). "In addition, AKR1C1 promotes cancer metastasis and clinically is correlated with poor prognosis." (PMID 35370661, 2022). "Moreover, tumor tissues with higher infiltrating levels of T cells CD8, T cells CD4 naive, T cells CD4 memory resting, T cells regulatory (Tregs), T cells gamma delta, dendritic cells resting and neutrophils had lower level of AKR1C1 expression on cancer cells." (PMID 34702254, 2021). "Furthermore, the experimental depletion of AKR1C1 (by either siRNA or shRNA) could effectively revert the metastasis of cancer cells, as well as their drug resistance 15, 17-19." (PMID 32104503, 2020).
cancer (continued). "AKR1C1-3 expression has been reported to be induced by anti-cancer agents, thus producing a consequent enhancement of the resistance mechanisms engaged by cancer cells against standard chemotherapics and the activation of survival pathways, thus facilitating cancer progression." (PMID 29515258, 2018). "As a result, inhibition of 17β-estradiol by AKR1C1 may recover cell motility in cancer cells." (PMID 27698389, 2016). "To investigate the relationship between TSPO and ferroptosis in MPNST, we used RT-qPCR to detect the differential mRNA expression levels of two classic ferroptosis biomarkers, AKR1C1 and FTH1, in tissues from patients with benign and malignant tumors." (PMID 40842566, 2025). "AKR1C1/3 are up regulated in response to xenobiotic substances like cigarette smoke, a primary HNSC cancer etiological agent." (PMID 35912202, 2022). "ALA binds to AKR1C1 and shows strong suppression effect against AKR1C1, resulting in an inhibition of STAT3, to inhibit cancer proliferation and metastasis." (PMID 35370661, 2022). "An increasing number of studies have provided strong evidence that AKR1C1 is a key component in the STAT3 pathway, which is critical for metastasis in different cancer models." (PMID 35370661, 2022). "For example, the expression of two genes (AKR1C1 and AKR1C2) in carcinoma cells and stromal fibroblasts and their positive correlation are favorable tumor characteristics in primary BC patients." (PMID 35617355, 2022). "Taken together, AKR1C1 is involved in the development and progression of CCA, making it a potential new anti-cancer target." (PMID 34127944, 2021). "In addition, the low expression of AKR1C1 may slow down the progression of cancer." (PMID 34012402, 2021). "Among these, sulfotransferases (SULT1A1, SULT1A2, SULT1A3) and aldo-keto reductases (AKR1C1, AKR1C2, AKR1C3) were shown to contribute to disease progression and/or represent therapeutic targets in hormone-dependent forms of cancer, including EOC." (PMID 26372729, 2015). "Notably, specific mutations were observed in genes involved in lipid localization and transport, including AKR1C1, HDLBP, and ABCC3, suggesting disruptions in lipid metabolism that facilitate the rapid proliferation of cancer cells." (PMID 38010945, 2024). "Additionally, miR193a-CM upregulated genes for S100A8, AKR1C1, AREG, and PLIN2 were shown to inhibit angiogenesis and cancer growth." (PMID 36766731, 2023). "Thus, levels of AKR1C1 and AKR1C2 gene expression are consistently overexpressed, in smoking-related cancer and upon smoke exposure." (PMID 28467356, 2017). "Moreover, three members of aldo-keto reductases (AKRs), AKR1C1, AKR1C2, and AKR1C3, are overexpressed in cancer." (PMID 25243088, 2014). "We suggest that the up-regulations of the genes AKR1C1/C2, TM4SF1 and NR0B1 in SP of human adenocarcinoma A549 cells could be a target of poor prognosis in anti-cancer therapy." (PMID 18034892, 2007). "AKR1C1/AKR1C3 was known to inactivate progesterone, which could alter the progesterone/estrogen ratio in certain cancers." (PMID 18034892, 2007). "The present work demonstrates that AKR1B10, AKR1C1, AKR1C2 and AKR1C3 are transcriptional targets strongly indicative of NRF2 status in human tumours, and that NRF2 is the upstream effector of AKR overexpression in cancer, particularly in tumours of squamous origin." (PMID 27824809, 2016). "Therefore, enrichment of AKR1C1/C2, TM4SF1 and NR0B1 in SP of A549 cells might be a target of poor prognosis in cancer therapy." (PMID 18034892, 2007).
tumor (59 papers, 2009 to 2025). "By comprehensively assessing the expression of 19 genes in NB tumor samples and cell lines, it was discovered that the mRNA expression level of AKR1C1 was significantly elevated in both high-risk NB groups and SK-N-BE2 (MYCN amplification NB cell line)." (PMID 39964621, 2025). "This allowed us to unravel hallmark gene signatures of the tumor-normal ecosystems, outline distinctions between AKR1C1+ and WNT5A+ inflammatory fibroblasts, and characterize TLS-enriched and non-enriched cell types among immunotherapy-favorable components." (PMID 38744958, 2024). "Overexpression of cdk6 in tumor cell lines having low cdk6 resulted in decreased levels of mRNAs encoding aldo-keto reductase (AKR)1C1, AKR1C2 and AKR1C3, which are hydroxysteroid dehydrogenases (HSDs) involved in steroid hormone metabolism." (PMID 24848372, 2014). "Taken together, these findings suggest that AKR1C1 overexpression is closely associated with ECC tumor progression and may be potentially used as a diagnostic and prognostic marker for ECC." (PMID 39478199, 2025). "AKR1C1 down‐regulation was associated with advanced clinicopathological characters such as larger tumor size, more lymphatic nodes involvement, with metastasis and later clinical stages, while AKR1C1 down‐regulation was a good prognostic factor for overall survival (OS) in NPC patients." (PMID 32307891, 2020). "AKR1C1 expression was, however, significantly associated with the histological type (P < .001), tumour size (T classification) (P = .030), lymph node metastasis (N classification) (P = .040), distant metastasis (M classification) (P = .038) and clinical stage (P = .005)." (PMID 32307891, 2020). "Wogonin needs to be further investigated as an adjuvant in multidrug‐resistant NSCLC, especially when the tumor highly expresses AKR1C1/1C2." (PMID 41164269, 2025). "Collectively, AKR1C1 is a promising therapeutic target for ECC treatment through sensitizing ECC tumor tissue to ferroptotic cell death." (PMID 39478199, 2025). "Tumor growth decreased in mice treated with either imidazole ketone erastin (IKE) to induce ferroptosis or Dox diet to induce AKR1C1 knockdown, alone or in combination, in comparison with control mice." (PMID 39478199, 2025). "QBC939 cells with Dox-inducible depletion of AKR1C1 significantly impaired tumor growth, as indicated by tumor size, tumor volume, and tumor weight." (PMID 39478199, 2025). "Gefitinib impeded PDX tumor growth, and the pharmacological targeting of AKR1C1 by ALA further significantly decreased tumor volume." (PMID 40687611, 2025). "Aldo-keto reductase family 1 member C1 (AKR1C1) is one such enzyme that helps detoxify reactive lipid species, protecting tumor cells from lipid-induced oxidative damage." (PMID 40376583, 2025). "The results showed that AKR1C1 mRNA level was significantly upregulated in ECC tissues compared to that in the adjacent non-tumor tissues." (PMID 39478199, 2025). "In vivo and in vitro experiments reveal that the AKR1C1 inhibitor avasimibe inhibits OS cell proliferation and tumor growth by reducing the expression of AKR1C1 and FoxM1." (PMID 39964621, 2025). "AKR1C2 protein expression was correlated with survival outcomes in combination with clinicopathological data such as sex, HPV status, tumor status, smoking history, alcohol consumption, and protein expression levels of AKR1C1, AKR1C3, and NRF2." (PMID 39272833, 2024). "Aldo‐keto reductase family 1 member C1 (AKR1C1) was identified as a potential therapeutic target and demonstrated the inhibitory effect of aspirin and dydrogesterone as its inhibitors on tumor cells." (PMID 39418072, 2024). "Using the gene list expressed in these hotspots within the high-violence tumor samples, functional enrichment analysis revealed an upregulation of glucocorticoid biosynthesis in AKR1C1, AKR1C2, and NR4A1 overexpression, indicating altered cortisol synthesis." (PMID 38912926, 2024).
tumor (continued). "The AKR1C1 gene was shown to promote the drug resistance of tumor tissue to THP in vivo, which was similar to the results in vitro." (PMID 37173953, 2023). "By contrast, in the remaining seven patients, the expression of AKR1C1 in the recurrent tumor tissue was significantly higher than those in the initial tumor tissue." (PMID 37173953, 2023). "By contrast, in the experimental group with overexpression of AKR1C1, only multifocal necrosis, a small number of tumor cell necrosis, and nuclear fragmentation were noted." (PMID 37173953, 2023). "The tumor tissue volume and mass of the experimental group (overexpression of AKR1C1 genome) were significantly higher than those of the blank and the control group after receiving THP treatment." (PMID 37173953, 2023). "After HE staining of the sections of the three groups of tumor tissues, the area of cell death in the AKR1C1 overexpression group was lesser than those in the blank and negative control groups after THP treatment." (PMID 37173953, 2023). "Quantitative polymerase chain reactionanalysis of the mRNA expression in U-87 MG and SKOV-3 tumor tissuesfrom 15-treated mice showed the presence of Ptgs2/Nfe2l2/Sat1/Akr1c1/Gpx4 genes correlated with ferroptosis in bothgroups." (PMID 36395526, 2022). "Overexpression of AKR1C1 is shown to play an important role in tumor invasion, metastasis, and drug resistance." (PMID 35370661, 2022). "The immunohistochemical assay showed that the expression level of AKR1C1 protein in NSCLC tissues was significantly higher than in corresponding adjacent non-tumor tissues, which indicated that AKR1C1 was highly expressed in NSCLC." (PMID 34702254, 2021). "Our study figures out a new important function of AKR1C1 in addition to the field of tumor as well as suggests its application value in bone tissue engineering and diseases related with differential disorders of hASCs." (PMID 34233738, 2021). "We proved that avasimibe alone inhibited cell viability and tumor growth of human CCA cells by targeting the FoxM1/AKR1C1 signaling pathway." (PMID 34127944, 2021). "AKR1C1 was weakly or absently observed in the cytoplasm of normal bile duct cells, but dramatically increased in tumor cells." (PMID 34127944, 2021). "Another family of NRF2 effectors are the aldo-keto reductases (AKRs, AKR1B, AKR1C1/2 and AKR1C3) which are upregulated in many LUSC and some LUAD tumor biopsies with somatic mutations in the NFE2L2 gene." (PMID 34440648, 2021). "AKR1C1 has been proposed as a target for the anti-tumor compound wentilactone A in SCLC cells; indeed, the aldo-keto reductases are considered as biomarkers for NRF2 status in human tumors." (PMID 34440648, 2021). "In the study, we proved that avasimibe retard cell proliferation and tumor growth of CCAs and identified FoxM1/AKR1C1 axis as the potential novel targets of avasimibe." (PMID 34127944, 2021). "AKR1C1 was a promising predictor for tumor recurrence and overall survival and correlated significantly with FoxM1 expression in CCAs." (PMID 34127944, 2021). "Previous studies confirmed that AKR1C1 promotes tumor metastasis via phosphorylating STAT3 and its upstream kinase JAK2 (JAK2/STAT3 pathway)." (PMID 34938341, 2021). "Six overall survival associated genes (ENPP2, ULK1, CP, LURAP1L, HIC1, AKR1C1) were selected to build survival model, of which hub gene AKR1C1 was with high expression and low ferroptosis level in NSCLC tumor." (PMID 34702254, 2021). "Another drawback is that the survival outcomes of the patients providing these tumour specimens are unavailable, which hinder further evaluation of the prognostic role of AKR1C1 for NB patients." (PMID 32683778, 2020). "Several tumor suppression pathways including apoptosis and necrosis were suppressed by AKR1C1 expression." (PMID 31182137, 2019). "AKR1C1 expression activated several oncogenic functions including tumor cell viability, metastasis, and angiogenesis." (PMID 31182137, 2019).
tumor (continued). "For the orthotopic xenograft model, the metastatic tumor cells, particularly the liver and bone cells, possessed significantly higher expression levels of AKR1C1, AKR1C2 and AKR1C3, corresponding with increased cisplatin resistance." (PMID 27698389, 2016). "The genes of the SLC family such as SLC2A14 and SLC2A3 and the AKR1 (aldo-keto reductase 1) family such as AKR1C1, AKR1C2, AKR1C3 and AKR1B10 were associated with the metabolic processes of tumor cells." (PMID 20003295, 2009). "Overall, these results indicate that AKR1C1 plays a crucial role in promoting ECC tumor formation." (PMID 39478199, 2025). "We also employed a QBC939 cells-derived xenograft mouse model to investigate whether AKR1C1 expression is essential for tumor growth in vivo." (PMID 39478199, 2025). "Furthermore, we demonstrate that inducible AKR1C1 knockdown inhibits ECC tumor growth and triggers ECC cells to undergo ferroptosis." (PMID 39478199, 2025). "In addition, qRT-PCR analysis also showed that the extrahepatic CCA cell line QBC939 had a higher expression of AKR1C1 than cell lines of other tumor types." (PMID 39478199, 2025). "In addition, apoptosis and necrosis analysis showed that the number of apoptotic and necrotic tumor cells in the AKR1C1 knockdown groups were significantly increased compared with the si-NC group." (PMID 39964621, 2025). "In addition, we identified potential therapeutic agents, aspirin and dydrogesterone, that target aldo‐keto reductase family 1 member C1 (AKR1C1) and demonstrated their inhibitory effect on tumor cells." (PMID 39418072, 2024). "In a word, these results revealed the role of AKR1C1 in promoting tumor cell migration and inhibiting apoptosis, which can be mitigated by inhibitors, and provide a promising therapeutic option for AKR1C1 inhibitor treatment in patients with AKR1C1 overexpression." (PMID 39418072, 2024). "In addition, AKR1C1 is identified as a potential therapeutic target and demonstrated the inhibitory effect of aspirin and dydrogesterone as its inhibitors on tumor cells." (PMID 39418072, 2024). "Thus, compared to matched normal tissue, the mRNA levels for AKR1B10 and AKR1C1 were decreased in 39/48 and 28/48 tumour samples, respectively." (PMID 35204145, 2022). "Moreover, ALA inhibited tumor growth in vivo, and the inhibition of AKR1C1 and STAT3 activation were also found in the murine xenograft model." (PMID 35370661, 2022). "Based on our research, it may act mainly by affecting the hypoxia microenvironment in tumor cells and regulating the expression of AKR1C1." (PMID 36550099, 2022). "Then we checked the impact of AKR1C1 on NSCLC tumor survival rates by the Kaplan-Mayer plotter database." (PMID 34702254, 2021). "Our study demonstrates a novel positive regulatory between FoxM1 and AKR1C1 contributing cell growth and tumor progression of CCA and avasimibe may be an alternative therapeutic option for CCA by targeting this FoxM1/AKR1C1 signaling pathway." (PMID 34127944, 2021). "From survival analysis, AKR1C1 could be a vital predictor of tumor recurrence and prognostic factor." (PMID 34127944, 2021). "Accumulating data showed that AKR1C1 contributed to cisplatin resistance in multiple tumours." (PMID 32307891, 2020). "Taken together, these results suggest that AKR1C1 might contribute to tumor progression and prevent tumor cell death in HNSCC." (PMID 31182137, 2019). "In addition, AKR1C1 has been reported in various tumors that may lead to the tolerance of tumor cells to chemotherapy drugs, such as anthracycline compounds." (PMID 37173953, 2023). "Clinically, AKR1C1 is highly expressed in human ECC tissues and closely correlated with tumor progression and poor prognosis." (PMID 39478199, 2025). "Conversely, in tumor tissues with low TSPO expression, AKR1C1 and FTH1 are similarly found to have low expression." (PMID 40842566, 2025).